PTH (parathyroid hormone)
Diseases named in the same sentence as PTH in open-access papers (continued):
Sharing a sentence is not in itself a finding about the gene and the disease.
primary hyperparathyroidism (continued). "Primary hyperparathyroidism is an endocrine disorder with high prevalence characterized by an increased production of parathyroid hormone (PTH) from autonomous parathyroid tissue no longer responsive to physiological feed-back from serum calcium levels." (PMID 31380379, 2019). "Intact PTH is a significant determinant of serum sclerostin levels in healthy premenopausal and postmenopausal women, patients with primary hyperparathyroidism, HD patients, and PD patients, but not in patients with non-dialyzed CKD." (PMID 31315601, 2019). "Plasma PTH levels may be normal or raised in patients with FHH, similar to patients with primary hyperparathyroidism." (PMID 31723423, 2019). "Primary hyperparathyroidism (PHPT) is a common endocrine disease and is characterized by hyperactivity in one or several parathyroid glands, raised levels of parathyroid hormone (PTH) and altered calcium homeostasis with increased calcium levels in the circulation." (PMID 30300532, 2018). "We previously reported that infusion of angiotensin II in individuals without primary hyperparathyroidism (P-HPT) increased PTH levels by >30%." (PMID 28808443, 2017). "The objective of this study was to validate our approach of treating primary hyperparathyroidism using sestamibi scan directed parathyroidectomy, without routine use of intraoperative parathyroid hormone measurements (ioPTH)." (PMID 28166819, 2017). "Interestingly, similar multi-layered canopies have been observed in adult patients with primary hyperparathyroidism, who, like many young CKD patients also have high circulating PTH levels." (PMID 27045269, 2016). "These patients, who present with mild primary hyperparathyroidism, are less likely to show abnormal laboratory findings at diagnosis, and present serum calcium and PTH measurements not as elevated as patients with overt symptoms of the disease." (PMID 27812604, 2016). "It is of note that this patient’s serum parathyroid hormone level was not checked and therefore, normocalcemic primary hyperparathyroidism cannot be ruled out as a contributing factor to his symptoms." (PMID 26543719, 2015). "Among them, there were no cases of primary hyperparathyroidism, i.e. increased levels of both PTH and calcium, and no patient had estimated glomerular filtration rate < 30 ml/min/1.73 m2." (PMID 26078787, 2015). "Pleiotropic effects of PTH are also reflected by numerous nonskeletal, nontraditional manifestations of primary hyperparathyroidism." (PMID 24782595, 2014). "Serum calcium, phosphate and parathyroid hormone levels can be used to diagnose primary hyperparathyroidism considering that there are usually no specific clinical manifestations in parathyroid hyperplasia patients." (PMID 23554805, 2013). "Cross-reactivity with human PTH was relatively low, allowing only for measurement of elevated PTH levels (e.g., patients with primary hyperparathyroidism), but not normal to low levels of PTH." (PMID 22792251, 2012). "Until now superiority of the third generation of PTH kits, measuring only the concentration of “native” 1-84-PTH, has not been proven for diagnosis of primary hyperparathyroidism, at least in patients without chronic kidney disease." (PMID 21318141, 2010). "In addition, the PTH levels in both groups, although at the higher end of the normal range, remained lower than levels typical for primary hyperparathyroidism." (PMID 39865206, 2025). "In hypercalcaemic patients who had an indication for PA screening and had surgical treatment of their primary hyperparathyroidism, PTH normalised in 85% (21/25) and diastolic, but not systolic blood pressure, was significantly reduced (80.3 mmHg to 72.2 mmHg, p = 0.038)." (PMID 40608198, 2025).
primary hyperparathyroidism (continued). "Concurrently, elevated blood calcium and parathyroid hormone levels, along with 99mTc-methoxyisobutyl isonitrile (99mTc-MIBI) imaging revealing increased 99mTc-MIBI uptake in the right inferior parathyroid gland, suggest the consideration of primary hyperparathyroidism." (PMID 39736861, 2024). "There is evidence that high levels of calcium and low serum phosphorus (the biological aspects in primary hyperparathyroidism) alter the modulation of the insulin receptor, whereas excessive PTH concentration does not directly influence the insulin signal transduction pathway." (PMID 38928056, 2024). "However, studies on patients without the diagnosis of primary hyperparathyroidism (such as NHANES cohort) showed that high serum PTH is positively correlated with the severity of metabolic syndrome if PTH is elevated at baseline." (PMID 38928056, 2024). "Primary hyperparathyroidism (PHPT) is the third most prevalent endocrine disorder in Western countries after diabetes mellitus and thyroid diseases, characterized by increased calcium levels combined with elevated or inappropriately normal parathyroid hormone (PTH) levels." (PMID 36824357, 2023). "PTH circulating levels are mildly elevated which may lead to misdiagnosis of primary hyperparathyroidism (PHPT), since reliable distinctions are not always possible on clinical grounds." (PMID 34068220, 2021). "The tissue aspirate parathyroid hormone (PTH) assay was first introduced in patients with primary hyperparathyroidism in 1983 by Doppman, and it is now also applied in patients with persistent or recurrent primary hyperparathyroidism featuring high sensitivity and specificity." (PMID 33477403, 2021). "Consistently, in vitro experiments demonstrated a negative relationship between PTH and irisin, and these findings were further supported by the reduced concentration of the myokine in post-menopausal women with primary hyperparathyroidism with respect to the controls." (PMID 33656700, 2021). "The five patients who had preoperative PTH levels above the reference value were not excluded from the analysis because they did not have the diagnosis of primary hyperparathyroidism, given that their serum total calcium levels were at the lower limit of normality." (PMID 31340251, 2019). "More accurate imaging and use of intraoperative PTH levels may allow a less extensive initial parathyroidectomy (unilateral clearance, removing both parathyroids with cervical thymectomy) in selected MEN1 patients with primary hyperparathyroidism." (PMID 27402205, 2016). "Primary hyperparathyroidism with elevated PTH and calcium can present with a variety of psychiatric symptoms, and we previously reported that this may be due to elevated PTH and not elevated calcium." (PMID 24884774, 2014). "It was noticed that patients with primary hyperparathyroidism show increased numbers of circulating CD34+ EPCs in the peripheral blood concomitant with an increased PTH circulating levels, supporting the proportion that PTH can mobilize bone marrow cells into the blood circulation." (PMID 24503654, 2014). "Additionally, our in vitro studies suggest the existence of a negative interplay between PTH and irisin biology and these results were also supported by the observation that post-menopausal women with primary hyperparathyroidism have lower levels of irisin compared to matched controls." (PMID 31091695, 2019). "Moreover, our in vitro studies suggest the existence of a negative interplay between PTH and irisin biology and these results were also supported by lower levels of irisin observed in post-menopausal women with primary hyperparathyroidism compared to matched controls." (PMID 31091695, 2019). "Primary hyperparathyroidism (PHPT) is described as increased serum calcium and nonsuppressed parathyroid hormone (PTH) levels." (PMID 31385484, 2019).
primary hyperparathyroidism (continued). "Due to high penetrance of primary hyperparathyroidism in MEN-1, serum calcium and PTH are the first step to rule out the diagnosis." (PMID 25038902, 2014). "The usefulness of PTH–FNA for localizing and differentiating an atypical functional parathyroid lesion from nonfunctional tissue in primary hyperparathyroidism is thus evident from the report." (PMID 25379182, 2014).
chronic kidney disease (538 papers, 2007 to 2026). Impairment of the renal function secondary to chronic kidney damage persisting for three or more months. "The slower rate of degradation and clearance causes accumulation of oxidised PTH and PTH-fragments predominantly in patients with chronic kidney disease (CKD)." (PMID 40362516, 2025). "One such study reported an increased risk in patients with elevated parathyroid hormone (PTH) concentration treated with peritoneal dialysis for chronic renal failure, compared to those with normal PTH levels." (PMID 40149408, 2025). "The majority of patients affected by calciphylaxis have predisposing comorbidities such as end-stage renal disease with a long history of hemodialysis and electrolyte abnormalities in calcium, phosphate, and parathyroid hormone levels." (PMID 38765385, 2024). "Mineral and bone disease in children with chronic kidney disease can cause abnormalities in calcium, phosphorus, parathyroid hormone, and vitamin D and when left untreated can result in impaired growth, bone deformities, fractures, and vascular calcification." (PMID 37964112, 2024). "Stage 5 or end-stage renal disease is marked by low serum calcium levels, high phosphate and low calcitriol levels, which further increase PTH, causing secondary and, in chronic cases, tertiary hyperparathyroidism." (PMID 37375708, 2023). "A meta-analysis showed weak associations between serum PTH and the risk of death and cardiovascular events in patients with chronic kidney disease." (PMID 35634511, 2022). "The aim of the study was to evaluate the association between serum calcium (Ca), phosphate (P), intact parathyroid hormone (iPTH), and 25(OH) vitamin D levels and mortality risk, in a chronic kidney disease (CKD) grade (G) 3b-4 cohort." (PMID 35946486, 2022). "Multiple investigations should be conducted to discover the specific cause of calcification in high-risk populations, such as assessments of parathyroid hormone, vitamin D, phosphate, calcium, and renal function to evaluate for chronic kidney disease." (PMID 35227302, 2022). "Further, another cohort study by De Boer and colleagues demonstrated that the association between parathyroid hormone and chronic renal insufficiency differed across races." (PMID 33725210, 2021). "Results of clinical studies investigating the association between parathormone (PTH) and fat mass in patients with chronic kidney disease (CKD)." (PMID 34422722, 2021). "Another study demonstrated that parathyroid hormone was associated with p450 downregulation in chronic renal failure cases." (PMID 34680932, 2021). "Abundant studies reported no statistically prominent difference in terms of age, sex, duration of dialysis, etiology of uremia, levels of PTH, calcium, phosphorus, and creatinine in association with pruritus among patients of end-stage renal disease." (PMID 34646616, 2021). "We aimed to examine the association of three mineral metabolism markers, including serum calcium, inorganic phosphorus, and intact parathyroid hormone with the risk of chronic kidney disease (CKD) at all stages." (PMID 33725210, 2021). "Abnormalities in serum calcium, phosphorus, and PTH concentrations are common in patients with chronic kidney disease and have been associated with increased cardiovascular calcification, arterial dysfunction, morbidity and mortality." (PMID 34620096, 2021). "Previously, serum PTH > 65 pg/mL was found associated with cardiovascular events in patients with chronic kidney disease (CKD) stages 3 and 4 and with progression of CKD as well as mortality in those with CKD stages 2–4." (PMID 31597282, 2019). "Decreased levels of parathyroid hormone are associated with regression of left ventricular hypertrophy, thereby reducing cardiovascular calcification and chronic renal failure mortality." (PMID 30988271, 2019).
chronic kidney disease (continued). "Cascade of changes in mineral metabolism occur in the course of chronic kidney disease resulting in the increase in the level of circulating parathyroid hormone and in abnormalities associated with secondary hyperparathyroidism (SHPT)." (PMID 29865146, 2018). "Characteristics of studies included in the meta-analysis for the relationship between VDR rs1544410 gene polymorphism and PTH level among patients with the end-stage renal disease." (PMID 29794776, 2018). "Results of meta-analysis for the association between VDR rs1544410 gene polymorphism and PTH level among patients with the end-stage renal disease." (PMID 29794776, 2018). "It was shown that in chronic kidney disease patients the decrease in GFR is associated with increased parathyroid hormone (PTH) levels." (PMID 28904363, 2017). "Mortality, due mainly to cardiovascular causes, was associated with low vitamin D levels and high parathyroid hormone in patients with chronic renal disease." (PMID 26000280, 2015). "Chronic excessive PTH levels are frequent in end-stage renal disease (ESRD) and are associated with parathyroid hyperplasia and eventually autonomous secretion." (PMID 24495277, 2014). "Chronic kidney disease is associated with disruption of the endocrine system that distorts the balance between calcitriol, calcium, phosphate and parathyroid hormone in the calcium regulation system." (PMID 23865435, 2013). "In the current study, we showed that serum UA was associated with LV hypertrophy independently of PTH levels and other possible confounders, including age, high blood pressure chronic kidney disease, and FGF23 level, in cardiac patients." (PMID 24340056, 2013). "Brown’s tumor is a non-neoplastic, reactive lesion caused by HPT, with primary disease referring to pathology directly affecting the parathyroid gland, secondary disease resulting from chronic kidney disease, and tertiary disease caused by autonomous PTH secretion." (PMID 41503329, 2025). "Parathyroid hormone (PTH) is a pivotal hormone that regulates serum calcium and phosphate and is closely associated with higher risk of cardiovascular disease and mortality in patients with chronic kidney disease (CKD)." (PMID 39829956, 2024). "Univariate Logistic regression analysis showed that advanced age, plasma homocysteine, blood parathyroid hormone, hyperphosphatemia, hypertension, high volume load and left ventricular hypertrophy were risk factors for death in patients with chronic renal failure on maintenance hemodialysis." (PMID 37680805, 2023). "Additionally, alterations in mineral metabolism, such as elevated levels of parathyroid hormone (PTH) and phosphorus, are commonly observed in chronic renal failure and have been associated with muscle weakness and reduced exercise capacity." (PMID 37954830, 2023). "Administration of cinacalcet, an alternative ligand of calcium-sensing receptor decreasing the production of parathyroid hormone and thereby lowering serum calcium and phosphate, to the patients with chronic kidney disease reduced the risk of major adverse cardiovascular events." (PMID 36499266, 2022). "However, some studies have reported only a weak association between serum PTH and the risk of death in patients with chronic kidney disease." (PMID 35634511, 2022). "Abnormalities in serum parathyroid hormone (PTH) are exceedingly common in end-stage renal disease (ESRD) patients on maintenance dialysis and associated with cardiovascular disease, disturbances in bone mineral disorders, even increased morbidity and mortality in most epidemiologic studies." (PMID 33514340, 2021). "Some prior studies have deduced the association between elevated PTH levels and myocardial damage or even HF in patients with chronic renal insufficiency by investigating the B-type natriuretic peptide level, NYHA, myocardial infarction, or HF history, or in animal models." (PMID 33691727, 2021).
chronic kidney disease (continued). "However, a previous study showed that, in a cohort of 278 participants with chronic kidney disease, 24,25(OH)2D (R = −0.44, P < 0.001) showed stronger association with PTH than that with 1α,25(OH)2D (R = −0.16, P = 0.01) or 25(OH)D (R = −0.22, P < 0.001)." (PMID 33606762, 2021). "It is well documented that disturbance in vitamin D, phosphorus, calcium and PTH metabolism contributes to bone disorders and cardiovascular complications of end stage renal disease patients and is associated with the morbidity and mortality of this population." (PMID 23133549, 2012). "Chronic kidney disease (CKD) is associated with many disturbances in the homeostasis of calcium, phosphate, parathyroid hormone (PTH), calcitriol, fibroblast growth factor 23 (FGF23), and Klotho." (PMID 41303166, 2025). "In chronic kidney disease (CKD) patients, elevated parathyroid hormone (PTH) is linked to cardiovascular mortality and morbidity." (PMID 39791168, 2025). "Chronic kidney disease (CKD) causes a dysregulation of the parathyroid hormone (PTH), fibroblast growth factor 23 (FGF23) and vitamin D homeostasis, which induces abnormalities of calcium and phosphate metabolism." (PMID 40141345, 2025). "Chronic kidney disease (CKD) is a condition characterized by an irreversible loss of renal function, accompanied by imbalances in calcium, phosphate, parathyroid hormone (PTH), and vitamin D levels." (PMID 39246913, 2024). "The disruptions in mineral metabolism caused by CKD, rising PTH, and lower vitamin D levels are presently recognized as integral components of the chronic kidney disease–mineral and bone disorder (CKD–MBD) definition." (PMID 38792638, 2024). "Abnormalities in calcium, phosphorous, and PTH, hallmarks of the condition known as chronic kidney disease – mineral and bone disorder (CKD-MBD), are associated with adverse outcomes in patients receiving maintenance dialysis." (PMID 37730530, 2023). "The decline in kidney function in patients with chronic kidney disease (CKD) is associated with increasing serum phosphate, decreasing serum calcium, and increasing parathyroid hormone (PTH) concentrations." (PMID 34136780, 2021). "Excess levels of PTH are associated with chronic kidney disease–mineral and bone disorder (CKD–MBD), which results in a loss of calcium from the bones with the subsequent increase of calcium levels in the blood." (PMID 30159688, 2019). "Chronic kidney disease (CKD) causes the parathyroid hormone concentration ([PTH]) to rise to abnormally high values." (PMID 28445401, 2017). "Abnormalities of bone turnover are commonly observed in patients with chronic kidney disease (CKD), and the low‐turnover bone disease is considered to be associated with low serum parathyroid hormone (PTH) levels and skeletal resistance to PTH." (PMID 28781957, 2017). "Patients with elevated PTH were older and had a higher burden of chronic kidney disease, cardiovascular disease, and inflammatory and nutritional abnormalities." (PMID 41899208, 2026). "Age, history of cardiomyopathy, severe chronic renal failure, serum PTH concentration, serum CRP concentration and use of systemic corticosteroids were associated with 6-months mortality in unadjusted model but not in the fully-adjusted model." (PMID 40882292, 2025). "PTH levels in both groups were below the normal reference range except for two chronic renal failure patients with normal low PTH levels." (PMID 40284609, 2025). "Age, history of cardiomyopathy, severe chronic renal failure, serum PTH concentration, serum CRP concentration and use of systemic corticosteroids were associated with 2 year mortality in unadjusted model but not in the fully-adjusted model." (PMID 40882292, 2025). "The presence of a parathyroid adenoma, elevated PTH levels, chronic kidney disease requiring dialysis, and specific imaging findings suggest a potential diagnosis of brown tumor of the bone." (PMID 40922257, 2025).